AQP4 (aquaporin 4)
Diseases named in the same sentence as AQP4 in open-access papers (continued):
Sharing a sentence is not in itself a finding about the gene and the disease.
brain edema (continued). "Several studies have demonstrated that the level of AQP4 expression is up-regulated in cytotoxic cerebral edema, and when AQP4 expression is down-regulated, the brain edema is reduced." (PMID 35260880, 2022). "Wallisch33 reported that pharmacological AQP4 inhibition significantly reduced pediatric asphyxial CA-related cerebral edema and improved neurobehavioral outcomes." (PMID 35177771, 2022). "In vasogenic cerebral oedema, AQP4 plays an important role in improving oedema, which was confirmed by the significantly reduced rate of resolution of cerebral oedema in AQP4 knockout cells." (PMID 36582214, 2022). "For a closer inspection of the TRPV4 and AQP4 channel complex in the development of brain edema, we applied a real-time iontophoretic method in situ to determine ECS diffusion parameters, namely volume fraction (α) and tortuosity (λ)." (PMID 36568889, 2022). "AQP4 expression is also sharply increased in ischemic brain edema, and AQP4-ko or inhibitor administration has been shown to be effective in reducing cellular edema." (PMID 36685250, 2022). "Early inhibition of AQP4 expression has been shown to reduce brain edema and improve posttraumatic recovery." (PMID 33880700, 2021). "Since studies have determined the involvement of AQP4 in the process of cerebral edema in early 2000, AQP4 has become a hot research." (PMID 34483842, 2021). "AQP4, an aquaporin protein, exerts a crucial effect on the pathogenesis of brain edema and affects the prognosis of IS." (PMID 34367186, 2021). "The unique advantage of AQP4 in regulating water transport determines its crucial position in cerebral edema." (PMID 34867201, 2021). "This question should not hinder the research community in further search for treatment strategies, in which the pivotal position of AQP4 in cerebral edema management is utilized for the improvement of outcome and neuronal protection." (PMID 34966347, 2021). "AQP4, one of the water channel proteins, is a key factor in the development and resolution of cerebral edema." (PMID 33397513, 2021). "AQP4 is a key mediator of CNS water influx and efflux, with a complex effect on cerebral edema, given its role in both edema formation and clearance." (PMID 34769328, 2021). "Several studies have shown increased levels of AQP4 after a head injury and have demonstrated its role in the incidence of cerebral edema." (PMID 32874565, 2020). "Various parameters are used as a marker for cerebral edema and as a therapeutic target of cerebral edema, including aquaporin-4 (AQP4), which is induced by astrocytes after a head injury." (PMID 32874565, 2020). "Accordingly, the use of AQP4 inhibiting agents is thought to play a role in controlling cerebral edema." (PMID 32874565, 2020). "In cerebral edema and ischemia, AQP4 expression is increased, and inhibition of AQP4 activity, either by knockout or pretreatment with an inhibitor has been shown to cause a reduction in edema size and formation." (PMID 32111087, 2020). "LITUS stimulation can significantly inhibit the expression of AQP-4 in the damaged areas and regulate the occurrence and development of cerebral edema after a TBI." (PMID 33281713, 2020). "Both Poldip2 siRNA and UK383367 improved neurobehavioral outcomes, alleviated brain edema, preserved the integrity of BBB, and relieved the loss of AQP4 polarity in BM model." (PMID 32790044, 2020). "Administration of CAPE in a rat subject with a head injury can reduce cerebral edema, mediated by AQP4." (PMID 32874565, 2020). "As has been described that early exercise initiated at 24 h after onset of ischemic brain injury for 3 days ameliorates brain edema, the present one-time exercise showed a tendency to suppress the expression of AQP4, a responsible factor for brain edema." (PMID 31720487, 2019).
brain edema (continued). "Regardless of the exact role, these sometimes contradictory studies indicate the importance of AQP4 in the pathogenesis of edema and suggest that AQP4 is an ideal drug target in combatting brain edema." (PMID 31187032, 2019). "Severe hypoglycemia induces brain edema by upregulating aquaporin-4 (AQP4) expression and by degrading tight junctions." (PMID 29793504, 2018). "Of the 6 kinds of the aquaporins expressed in the brain, aquaporin 4 (AQP4) is the most widely studied and is involved in potential mechanisms for cerebral edema." (PMID 30483388, 2018). "In contrast, in vasogenic edema, the role of AQP4 channels seems to be beneficial by facilitating the reabsorption of excessive fluid and thus the clearance of brain edema." (PMID 30333785, 2018). "It was suggested that carvacrol exerts its protective effect on ICH injury by ameliorating AQP4-mediated cerebral edema." (PMID 29721498, 2018). "In rats undergone hypobaric hypoxia, puerarin was able to elicit protective effects against cerebral edema by inhibiting the increase of AQP4 through inhibition of TNF-α release and by counteracting the activation of NF-κB and MAPK pathway." (PMID 29721498, 2018). "Modulation of brain AQP4 was reported in a preclinical study employing a bacterial collagenase-induced ICH murine model to address the effect of the monoterpenoid on cerebral edema after ICH." (PMID 29721498, 2018). "During the formation of cerebral edema, the water channel aquaporin 4 (AQP4) facilitates astrocyte swelling, and AQP4 mediates the reabsorption of extracellular edema fluid." (PMID 29234383, 2017). "We further studied the relationship between mGluR5 and AQP4 after brain edema using a rat model of tMCAO." (PMID 28503134, 2017). "Altered AQP4 expression has been observed in a number of conditions including cerebral edema, neuromyelitis optica, epilepsy, brain tumor, Alzheimer’s disease, Parkinson’s disease, depression and drug addiction." (PMID 28503134, 2017). "Secondary cerebral edema regulation is of prognostic significance in hypoxic-ischemic encephalopathy (HIE), and aquaporin 4 (AQP4) plays an important role in the pathogenesis of cerebral edema." (PMID 29234383, 2017). "Among all of the aquaporins, aquaporin-4, expressing on the end-feet of astrocytes, has been under extensive investigation and is emerging as a novel therapeutic target in cerebral edema intervention." (PMID 27690011, 2016). "Aquaporin-4 (AQP4) is the most abundant water channel in the brain and crucial for the formation and resolution of brain edema." (PMID 27529222, 2016). "Several pharmaceutical chemicals targeting at aquaporin-4 have shown positive effects on cerebral edema in both humans and animals." (PMID 27690011, 2016). "Expression levels of AQP4 mRNA have been shown to be elevated in the injured area compared to other brain areas, and the degree of expression correlates to the severity of cerebral edema as measured by MRI." (PMID 28036023, 2016). "Because HS can alleviate cerebral oedema by down-regulating aquaporin-4 by us, it was reasoned that it would also protect BBB permeability in the acute phase of cerebral oedema." (PMID 27733124, 2016). "As a significant channel of fast-flowing water in acute primary cerebral oedema, AQP4 functions in the exchange of water between normal physiological processes and cerebral ischaemia." (PMID 24520266, 2014). "The correlations between ADC values and the brainstem AQP4 expression at different time points suggest that AQP4 expression follows an adaptative profile to the severity of brain edema." (PMID 24282821, 2013). "The correlations between ADC and the brainstem AQP4 expression at different time points suggest AQP4 expression follows an adaptative profile to the severity of brain edema." (PMID 24282821, 2013). "The expression of AQP4 after TBI is time-dependent, region-specific, and possibly implicated in the formation and resolution of TBI-induced cerebral edema." (PMID 24282821, 2013).
brain edema (continued). "AQP4 null mice have lower mortality and are less prone to cytotoxic brain edema, including water intoxication cerebral edema, early focal cerebral ischemia and bacterial meningitis." (PMID 23036239, 2012). "Most importantly, theloss of AQP4 polarized distribution in thesemice resulted in a beneficial effect as it delayed the onset of brain edema." (PMID 21408176, 2011). "Further in vivo experiments aiming at investigating the role of flunarizine in models of cytotoxic brain edema addressing particularly its effect on DG and AQP4 perivascular distribution are warranted." (PMID 21408176, 2011). "The development of AQP4 modulating agents should be the future of molecularly targeted cerebral edema therapy." (PMID 21119879, 2010). "AQP4 over-expression in human astrocytomas correlates with detection of brain edema on magnetic resonance imaging." (PMID 21119879, 2010). "Drugs that target AQP4 function would provide a major therapeutic advancement in the treatment of all forms of cerebral edema, working synergistically with current therapies." (PMID 21119879, 2010). "In the present study, we found that in the rat RIBI model, radiation promoted the expression of AQP4, and the expression level of AQP4 was linearly correlated with the severity of cerebral edema, and radiation also induced a “depolarization” of AQP4 distribution." (PMID 40406486, 2025). "Abundant evidence indicates that AQP4, the most prevalent AQP in the CNS, regulates brain water transport and contributes to both cytotoxic and vasogenic edema, suggesting that AQP4 may serve as a potential therapeutic target for brain edema." (PMID 39944892, 2025). "The expression level of AQP4 correlated with the severity of cerebral edema." (PMID 40406486, 2025). "From this perspective, down-regulation of AQP-4 expression could reduce brain edema and produce therapeutic effects in patients with hepatic encephalopathy complicated by brain edema." (PMID 37307828, 2024). "Research has shown that AQP4 is significantly involved in the formation of cerebral edema." (PMID 39619615, 2024). "Astrocytic Transient receptor potential vanilloid 4 (TRPV4) channels, together with Aquaporin 4 (AQP4), are suspected to be the key players in cellular volume regulation, and therefore may affect the development and severity of cerebral edema during ischemia." (PMID 38818517, 2024). "This disruption could potentially lead to subarachnoid hemorrhage and brain edema, given AQP4's role in astrocyte-mediated regulation of brain water balance." (PMID 39564022, 2024). "Therefore, it is important to find the balance between the two roles of AQP-4 in exerting enhanced lymphatic drainage and reducing cerebral edema." (PMID 37307828, 2024). "Intervention of AQP4 expression on the surface of brain cells may be an effective method to treat cerebral edema after TBI." (PMID 37213674, 2023). "The hypothesis that Aquaporin-4 has a dual role in cerebral edema—being deleterious during edema formation while beneficial during its resolution—has gained empirical support despite the absence of conclusive evidence." (PMID 37762642, 2023). "AQP4 may play an important role in the exacerbation and resolution of traumatic cytotoxic brain edema." (PMID 37108515, 2023). "Previous studies have indicated that AQP4 is involved in the development of brain edema." (PMID 36248855, 2022). "The activation of aquaporin-4 (AQP4) is also an important mechanism affecting brain oedema, wherein water molecules enter brain tissues in large quantities through the activated AQP4 and then aggravate brain oedema and neuronal necrosis in cytotoxic cerebral oedema." (PMID 36582214, 2022). "The increase in aquaporin-4 concentration observed in the authors’ own research within the second postoperative day suggested significant disturbances in BBB permeability resulting in cerebral edema." (PMID 35627746, 2022).
brain edema (continued). "To test the hypothesis that AQP4 is a potential drug target for TBI via aggravating the severity of brain edema, we intravenously injected neutralized-AQP4 antibody in rats within 30–60 min after TBI and investigated the acute outcome of brain edema formation." (PMID 35177771, 2022). "Another study showed that curcumin could decrease the expression of AQP4 levels in the brain and reduce brain edema." (PMID 34630953, 2021). "Limiting AQP4 expression by use of small interfering RNAs (siRNA) to suppress the translation process is another viable option, efficiently reducing the development of posttraumatic brain edema, at least in animal models." (PMID 34966347, 2021). "Hence, the strategy of drug repurposing will open a fast track for the search for efficient AQP4-targeted treatment of brain edema." (PMID 34966347, 2021). "More comprehensive reviews focusing on AQP4’s role in cerebral edema have been reviewed elsewhere." (PMID 34769328, 2021). "AQP4 played an important role in regulating water balance in brain tissue, contributed to the reabsorption of cerebrospinal fluid and osmotic equilibrium, and closely related to the occurrence of cerebral edema." (PMID 33013433, 2020). "While downregulating the expression of miR-320a seems to be beneficial in cases of cerebral edema, in glioma cases this could have a detrimental effect, as miR-320a was found to inhibit glioma cell invasion and migration by targeting human AQP4 (hAQP4)." (PMID 32111087, 2020). "Administration of CAPE in a rat model with head injury can reduce cerebral edema, mediated by AQP4." (PMID 32874565, 2020). "The process of cerebral edema is mediated by several mediators, including AQP4 and cytokines." (PMID 32874565, 2020). "Therefore, it has a high possibility of claim that there are very close correlation between the reduction of AQP-4 and Nrf-2 expressions during scedosporiosis-induced cerebral oedema." (PMID 31080825, 2019). "AQP4, a water channel protein, plays a major role in the pathogenesis of cerebral edema." (PMID 31920554, 2019). "AQP4 plays an important role in the formation and dissipation of a cerebral edema, and has become a potential target for the treatment of cerebral edemas." (PMID 31572219, 2019). "AQP4 inhibitors or down regulators may provide future potential treatment of some conditions such as for cytotoxic brain edema." (PMID 30691235, 2019). "The expression of AQP-4 was also proven to be significantly up-regulated in cerebral edema under hypobaric hypoxia and to inhibit its expression could lead to preventative effect." (PMID 29592873, 2018). "The effect of MFG-E8 on the reduction of brain edema might be through the modulation of the protein of AQP4." (PMID 30154436, 2018). "We also presumed, that AQP4 level correlates with extent of brain edema." (PMID 30333785, 2018). "In addition, acupuncture or EA at the Baihui (GV20) and left Zusanli (ST36) acupoints in rat model significantly reduces the expression of the proinflammatory enzyme MMP2 and the water channel proteins AQP4, to relieve inflammation related brain edema." (PMID 30356696, 2018). "In the present study, we found that AQP4 mediated glutamate-induced astrocyte swelling, which may provide new therapeutic targets for brain edema therapy." (PMID 28503134, 2017). "The redistribution and the displaced insertion of AQP4 molecules, which are a consequence of severe alterations of the microenvironment, are part of a set of stereotypical responses leading to the most serious clinical signs of glioblastoma—brain edema." (PMID 28423683, 2017). "That is to say, AQP-4 plays a two-way regulatory role in cerebral edema after CO poisoning." (PMID 27833554, 2016). "AQP4 plays an important role in the formation and clearance of brain edema, and appropriate regulation of AQP4 may treat brain edema from perspectives of mechanism as a remedy of the disadvantages of the current common treatment, such as dehydrant or surgery." (PMID 27529222, 2016).
brain edema (continued). "The beneficial effects on brain edema may at least partially be attributed to the block of the aquaporin-4 upregulation through the attenuated cytokines’ release." (PMID 27690011, 2016). "The regulation of AQP4 has been extensively investigated in various neuropathological conditions such as cerebral edema, epilepsy, and ischemia, however, the functional role of AQP4 in synaptic plasticity, learning, and memory is only beginning to be elucidated." (PMID 26941623, 2016). "As aquaporin-4 has shown a critical role in the progression of cerebral edema, it could be a promising target for the intervention." (PMID 27690011, 2016). "Our results showed that the dynamic change of AQP-4 protein expression after CO poisoning was consistent with the time of cerebral edema appearance, suggesting that AQP-4 plays various roles at different stages of the formation and dissipation in brain edema induced by CO poisoning." (PMID 27833554, 2016). "Aquaporin-4 plays a crucial role in the edema process in different brain pathologies, and its interference seems to be important for the recovery in the acute phase after cerebral edema." (PMID 27690011, 2016). "The increased expression of AQP-4 at an early stage of CO exposure (<3 days) might facilitate the formation and development of brain edema." (PMID 27833554, 2016). "Its restricted localization at the BBB and the down-regulation of AQP4 expression in AQP11-deficient brains suggest that AQP11 may play a role in the BBB water transport and in the pathophysiology of brain edema." (PMID 27258268, 2016). "Significance: Pharmacological modulation of AQP4 membrane localization could provide a new approach to treating brain edema." (PMID 26013827, 2015). "Aquaporin-4 plays an integral role in pathogenesis of brain edema." (PMID 26495025, 2015). "Thus, these AQP4 inhibitors are expected to show beneficial effects for clinical brain edema in future." (PMID 25941935, 2015). "In studies of brain edema, AQP4 has been extensively studied." (PMID 25941935, 2015). "On the other hand, another study suggested that AQP4 inhibition may provide a new therapeutic option for reducing brain edema." (PMID 24828425, 2014). "Thus, regulation of AQP4 after cerebral ischemia is a potential target for the treatment of cerebral edema." (PMID 24416250, 2014). "In the current study, we determined whether PROG alleviates BBB damage and cerebral edema by controlling the expression of AQP-4 and MMP-9." (PMID 23935758, 2013). "Early inhibition of AQP-4 expression in brain tissues may provide a new treatment protocol for cerebral edema." (PMID 23935758, 2013). "Recent studies have shown that AQP4 could be important in the formation and resolution of brain edema." (PMID 24282821, 2013). "In vasogenic brain edema, AQP4 increases the rate of edema fluid elimination." (PMID 17347837, 2007). "By promoting the AQP4 polarization to improve the GS function, it might facilitate the inflow of edema fluids, but it can also significantly enhance downstream drainage function, thereby reducing brain edema." (PMID 39944892, 2025). "Therefore, AQP4 serves as an essential indicator for assessing the occurrence of brain edema." (PMID 39619615, 2024). "But on the other hand, increased AQP-4 expression may also induce the formation of brain edema." (PMID 37307828, 2024). "In addition to constitutively expressed transporters like AQP4, Kir4.1 as an ATP-sensitive K+ channel could assemble with AQP4 to form a complex (water-ion transport coupling) that plays an important role in cerebral edema." (PMID 35474489, 2022). "Furthermore, the accelerated influx of water into the brain and elevated ICP in AQP4-overexpressing mice induced by intraperitoneal water injection confirm that the water channel protein promotes the occurrence of cerebral edema by increasing the permeability of the BBB." (PMID 34483842, 2021).